ANKRD27 (ankyrin repeat domain 27)
Description:
May be a guanine exchange factor (GEF) for Rab21, Rab32 and Rab38 and regulate endosome dynamics. May regulate the participation of VAMP7 in membrane fusion events; in vitro inhibits VAMP7-mediated SNARE complex formation by trapping VAMP7 in a closed, fusogenically inactive conformation. Involved in peripheral melanosomal distribution of TYRP1 in melanocytes; the function, which probably is implicating vesicle-trafficking, includes cooperation with Rab32, Rab38 and VAMP7 (By similarity). Involved in the regulation of neurite growth; the function seems to require its GEF activity, probably towards Rab21, and VAMP7 but not Rab32/38 (By similarity). Proposed to be involved in Golgi sorting of VAMP7 and transport of VAMP7 vesicles to the cell surface; the function seems to implicate kinesin heavy chain isoform 5 proteins, GOLGA4, RAB21 and MACF1. Required for the colocalization of VAMP7 and Rab21, probably on TGN sites. Involved in GLUT1 endosome-to-plasma membrane trafficking; the function is dependent of association with VPS29. Regulates the proper trafficking of melanogenic enzymes TYR, TYRP1 and DCT/TYRP2 to melanosomes in melanocytes (By similarity).
Synonyms: PP12899; FLJ00040; DKFZp434L0718; VARP
Tractability: Small molecule: a structure with a bound ligand is known. Antibody: UniProt places it where antibodies can reach, with high confidence; its Gene Ontology location is reachable by antibodies, with high confidence. PROTAC: ubiquitination databases record sites on it; its protein half-life has been measured.
Gene: Protein-coding gene on chromosome 19 (32,597,000 to 32,676,597, reverse strand). Ensembl gene ENSG00000105186.
Subcellular location: Early endosome; Late endosome; Cytoplasmic vesicle membrane; Lysosome; Cell membrane; Melanosome
Subcellular location (Human Protein Atlas): Vesicles; Cytosol
Pathways (Reactome):
Vesicle-mediated transport: RAB GEFs exchange GTP for GDP on RABs
Gene Ontology:
Molecular function: guanyl-nucleotide exchange factor activity; protein binding; small GTPase binding; SNARE binding
Biological process: early endosome to late endosome transport; endocytic recycling; negative regulation of SNARE complex assembly; neuron projection morphogenesis; endosome to melanosome transport; intercellular transport; positive regulation of dendrite morphogenesis; positive regulation of neuron projection development
Cellular component: cytoplasmic vesicle membrane; early endosome; late endosome; lysosome; membrane; plasma membrane; tubular endosome; cytosol; neuron projection; transport vesicle; cytoplasmic vesicle; endomembrane system; melanosome
Genetic constraint (gnomAD): Loss-of-function variants: 97 observed, 119.01 expected, observed/expected ratio (o/e) 0.82, 90% interval 0.69 to 0.96. The upper end of that interval is the gene's LOEUF score, 0.96, which puts it in group 4 of 6, group 1 being the genes least tolerant of losing a copy. Missense variants: 1,174 observed, 1,269.4 expected, observed/expected ratio (o/e) 0.92, 90% interval 0.88 to 0.97. Synonymous variants: 487 observed, 505.22 expected, observed/expected ratio (o/e) 0.96, 90% interval 0.89 to 1.04.
Homologues: Orthologues: chimpanzee ANKRD27 (99% identical), macaque ANKRD27 (97% identical), dog ANKRD27 (88% identical), pig ANKRD27 (88% identical), guinea pig ANKRD27 (86% identical), rabbit ANKRD27 (85% identical), mouse Ankrd27 (82% identical), rat Ankrd27 (82% identical), tropical clawed frog ankrd27 (61% identical), zebrafish ankrd27 (50% identical).
Diseases named in the same sentence as ANKRD27 in open-access papers:
ANKRD27 is named in the same sentence as 13 diseases in open-access papers, as found by Europe PMC text mining. Sharing a sentence is not in itself a finding about the gene and the disease. The quoted sentences say what the papers report.
colorectal cancer (1 paper, 2024). A primary or metastatic malignant neoplasm that affects the colon or rectum. "Moreover, ANKRD27 has been shown to participate in diseases prognosis, including eosinophilic esophagitis, Uveal Melanoma and colorectal cancer." (PMID 39834932, 2024).
esophagitis (1 paper, 2024). An acute or chronic inflammatory disease affecting the esophageal wall. "Ankyrin repeat domain 27 (ANKRD27, also known as VARP) has been reported to be implicated in the pathogenesis of esophagitis and respiratory diseases." (PMID 39834932, 2024).
hepatocellular carcinoma (1 paper, 2024). A malignant tumor that arises from hepatocytes. "We also examined ANKRD27 expression in hepatocellular carcinoma (HCC) patients using TCGA and GSE14520 datasets." (PMID 39834932, 2024).
measles (1 paper, 2023). A highly contagious viral infection caused by the measles virus. "In measles, including six in whole blood (SOAT1, COLGALT2, AC021860.1, HCG11, METTL21B, and MRPL10), six in the lung tissue (GSTM4, PAQR6, RP11-617D20.1, SNX8, METTL21B, and ANKRD27), and two in the transformed fibroblast cells (CBWD2, and TSFM)." (PMID 37020999, 2023).
ovarian carcinoma (1 paper, 2024). A malignant neoplasm originating from the surface ovarian epithelium. "To explore potential drugs targeting patients in the GMPI‐high group, we collected four ovarian cancer samples and calculated GMPI for each sample with the following formula: GMPI = 0.090* KIAA0100 + 0.043* ANKRD27 + 0.215* OPA3 + 0.171* NUMBL + 0.314* PDP1–0.233*SLC7A11–0.007* TRMT112." (PMID 38506093, 2024).
cancer (2 papers, 2020 to 2024). A tumor composed of atypical neoplastic, often pleomorphic cells that invade other tissues. "ANKRD27 displays abnormal levels of expression in different cancer types and is linked to immune status in cancer." (PMID 39834932, 2024). "Ankyrin repeat domain 27 (ANKRD27) has been found to be associated with certain cancers." (PMID 39834932, 2024). "The prognosis, cancer immunity, and drug sensitivity of patients with HCC are linked to abnormal ANKRD27 expression." (PMID 39834932, 2024). "ANKRD27 exhibited aberrant expression in multiple cancers and was correlated with immune traits, including immune infiltration, immune checkpoint genes, and immune modulatory genes." (PMID 39834932, 2024). "Expression analysis utilizing data from public datasets (TCGA and GTEx) revealed the dysregulated expression of ANKRD27 in multiple cancer types." (PMID 39834932, 2024). "ANKRD27 was aberrantly expressed in most cancers (eighteen cancer types), including LIHC, LAML, STAD, and others." (PMID 39834932, 2024). "ANKRD27 exhibited a significant negative correlation with the extent of immune cell infiltration in malignancies such as SARC, LUSC, ESCA, and UCSC, which implied that ANKRD27 might be involved in developing an immunosuppressive microenvironment in cancers." (PMID 39834932, 2024). "In the present study, we conducted assessment of the role of ANKRD27 in pan-cancer." (PMID 39834932, 2024). "Additionally, ANKRD27 expression was significantly linked to the levels of various genes related to immunostimulators, immunoinhibitors, chemokines, chemokine receptors, and MHC in a wide range of cancer types." (PMID 39834932, 2024).
ANKRD27 also shares sentences with these, for which no sentence is quoted: autoimmune thyroid disease (1 paper); eosinophilic esophagitis (1); infection (1); liver cancer (1); respiratory diseases (1); uveal melanoma (1); viral myocarditis (1).